GZMB (granzyme B)
Diseases named in the same sentence as GZMB in open-access papers (continued):
Sharing a sentence is not in itself a finding about the gene and the disease.
tumor (continued). "In addition, we detected increased tumor-infiltrating CD8+ T cells and enhanced CD8+ T-cell effector function as assessed by Granzyme B and IFN-γ expression in tumor-infiltrating CD8+ T cells from the ML323-treated group." (PMID 37996458, 2023). "In addition, T-BET– and EOMES-DKO NK cells harvested from tumor-bearing organs had reduced IFN-γ, granzyme B, and perforin compared with WT NK cells." (PMID 37279078, 2023). "The abundance of CXCL13+ CD4+ T cells, the tumor antigen‐specific T cells to immune‐checkpoint blockade, was significantly higher in primary tumors, and a subset of CD4+ T cells had high expression levels of several cytotoxic genes, including GZMB and GZMK." (PMID 37743226, 2023). "Moreover, regarding the cytotoxic function of CD8+ T cells, granzyme-B and INF-γ production decreased in B16-C8KO tumor cells." (PMID 36635765, 2023). "Tumor tissues with high DSE expression showed higher levels of IFNG, GZMB, and TNF expression." (PMID 37833287, 2023). "In addition, active granzyme B was detected in iRBC during NK-mediated ADCC, much like GzmB delivered into tumor target cells." (PMID 37939134, 2023). "The tumor immune microenvironment (TME) was remodeled and the activated anticancer immunity was characterized by the decreased immunosuppressive MDSC amount, and the increased NK cells, CD8+ T cells, cytotoxic substances granzyme B and INFγ." (PMID 37161591, 2023). "Moreover, activated B-cells can directly eliminate tumor cells by secretion molecules such as TNF-related apoptosis-inducing ligand (TRAIL) and granzyme B. These effector molecules induce apoptosis in tumor cells, contributing to their elimination." (PMID 38077386, 2023). "Immune-related genes, such as CD8A, CD8B, GZMA, GZMB, and PRF1, that may indicate the function of tumor-infiltrating CD8 + T cells were considerably enriched in the group receiving combination therapy." (PMID 37777634, 2023). "Granzyme B (GZMB) is an integral constituent of cytolytic granules found within natural killer (NK) cells and serves as a crucial cytotoxic molecule employed by T cells to eliminate cells infected by pathogens or transformed tumor cells." (PMID 38057716, 2023). "Therefore, we assessed the effect of combination treatment on T-helper lymphocytes (CD4+), cytotoxic lymphocytes (CD8+), activated lymphocytes (Granzyme B+), and antitumor macrophages (CD86 positive M1 type macrophages) infiltrating tumor tissue." (PMID 37640735, 2023). "Consistently, Arih1-C355S-OE tumors treated with anti-PD-L1 did not cause the accumulation of tumor-infiltrating CD8+ and GzmB+CD8+ T cells." (PMID 37429863, 2023). "Increased infiltration of GZMB+, IFN-γ+ CD8+ lymphocytes, and M1 macrophages in tumor tissue." (PMID 37111034, 2023). "Tumor-infiltrating CD8+ T cells were more activated (as reflected by the proportion of PD-1+TIM-3+ CD8+ T cells) and exhibited enhanced cytotoxicity (as reflected by Granzyme B and IFNγ levels)." (PMID 37500611, 2023). "None of the treatments increased the cytotoxicity markers granzyme B and perforin at the time of evaluation, which does not mean that in the face of direct activation with the tumor cell, a tumor-specific cytotoxic activity cannot be evidenced." (PMID 37464192, 2023). "To elucidate the underlying mechanisms associated with the improved therapeutic outcomes of DTIC/Epacasome-2, we then systemically investigated the NKG2D+(receptor), CD69+, IFN-γ+, Granzyme B+ or perforin+ NK and CD8+ T cells respectively, in tumours using flow cytometry." (PMID 37945606, 2023). "Controversially, kynurenine signaling through the AhR has been reported to promote the expression of the activating receptors NKp30, NKp46, perforin, and granzyme B in NK cells, which is supported by the observation that IDO1 inhibition impairs NK cell activity against tumor cells." (PMID 36713558, 2022).
tumor (continued). "EVs from the WT cells, but not TβRII null, led to a reduced cytotoxicity of tumor-infiltrating T cells (IFNγ+ or GZMB+ of CD8+ cells) and an increased exhaustion of tumor-infiltrating T cells (IFNγ+, PD1+ or TIM3+ of CD8+ cells)." (PMID 35915084, 2022). "In these tumor tissue, most pyroptosis-related molecules, particularly IRF1, GZMB, CASP5, BAK1 and AIM2, were consistently inhibited in the cell cycle, DNA damage response, hormone AR and RTK signaling pathway, but highly activated in the apoptosis signaling way." (PMID 36437960, 2022). "Through flow cytometry analysis, we found that CD39i treatment promoted T-cell proliferation and enhanced T-cell tumor killing function by secreting more granzyme B and perforin, but not IFN-γ." (PMID 36347860, 2022). "Consequently, anti-tumor effector molecules, such as IL2, IFNγ, TNFα, and granzyme B (GZMB), is dramatically downregulated in the CTLs and NK cells, and immune exhaustion and dysfunction are provoked locally and systemically in the host." (PMID 36211375, 2022). "Furthermore, AHA treatment also significantly increased levels of granzyme B and perforin in both Met1 and BT474-IdeS tumor models." (PMID 36104515, 2022). "Mice treated with the combination of AHCC® and DICB had increased expression of the cytotoxic molecule granzyme B, the cell proliferation marker Ki-67, and the cell activation marker CTLA-4 by tumor infiltrating CD8+ T cells compared to mice treated with water and DICB." (PMID 35514996, 2022). "Similar proportions of CD56dim/CD16+ NK cells isolated from the tumor microenvironment of NSG‐Tg(Hu‐IL15) mice express functional markers CD69, CD8, and NKG2D, and produce granzyme A and granzyme B when compared to NSG mice." (PMID 35959876, 2022). "In mouse tumor models (B16 melanoma and MC38 colorectal), a lack of the prostaglandin receptors EP2 and EP4 specifically on granzyme B+ cells – predominantly NK cells – causes tumor regression." (PMID 35844626, 2022). "Among them, the expression levels of CD8A, CD8B, GZMA, GZMB, and PRF1 were used to evaluate the infiltration levels of tumor cytotoxic T lymphocytes (CTLs), and a high-CTL-infiltration group has been related to significantly prolonged survival time of patients receiving immunotherapy." (PMID 36405701, 2022). "Although the percentage of granzyme B-positive cells was not altered, the absolute numbers in both spleen and tumor were increased upon MPCi conditioning." (PMID 35452600, 2022). "The populations of tumor-infiltrating NK cells and NK cells expressing granzyme B were not significantly changed." (PMID 35785192, 2022). "Cumulatively, these data suggest that granzyme B is predominantly expressed in the tumor and likely did not contribute to the killing mechanism described here." (PMID 35392082, 2022). "Immunohistochemically, the staining results of tumor cells in the small intestine and kidney were consistent; the tumor cells were positive for CD3, CD56, granzyme B, TIA-1, and perforin, while negative for CD4, CD8, CD5, Desmin, CD34, CKpan, CD20, CD30, SMA, CD79ɑ, and PAX8." (PMID 36199094, 2022). "Upon application of atezolizumab, an mAb medication against PD-L1, PD-L1+ NK cells express significantly increased levels of granzyme B, IFN-γ, and CD107a, which results in a significant increase in antitumor activity and ultimately a significant decrease in tumor burden in mice." (PMID 35634343, 2022). "Moreover, G9668 treatment led to significantly greater numbers of tumor-infiltrating cytotoxic CD8+ T cells and higher expression by these cells of the activation markers granzyme B, PD-1, and CD44." (PMID 35446348, 2022). "One striking difference was the increase in IFNγ + and granzyme B (GZMB) expressing cytotoxic CD8s after vaccination, which could have potential anti-tumour activity." (PMID 36307410, 2022).
tumor (continued). "Subsequently, we analyzed SQLE expression and its association with biomarkers of MHC (B2M, HLA-B, HLA-C, TAP1, and TAP2), dendritic cells (BATF3), macrophages (CD68 and IL1A), type-I anti-tumor responses (CD8A and GZMB), and cell proliferation (MKI67) in 178 PAAD tissues." (PMID 35720314, 2022). "Pioneering studies have recently been conducted to develop a 68Ga-labeled linear peptide GZP–based granzyme B–targeting radiotracer, 68Ga-1,4,7–triazacyclononane-1,4,7-triacetic acid–GZP (68Ga-NOTA-GZP), for PET monitoring of tumor immunotherapy in mouse models." (PMID 35788116, 2022). "Interestingly, we observed that the effects of BRB-E on Granzyme B production by CD8+ T cells were restricted to the primary tumor site, suggesting a potential link to BRB effects on CD4+ FoxP3+ Tregs in the tumor microenvironment." (PMID 36016924, 2022). "Moreover, outside of the tumor, splenic CD8 T cells from lean and obese mice secreted similar levels of IFN-γ, TNF, and GzmB and expressed similar levels of CD69, CD44, CD36, Eomes, and T-bet." (PMID 35103755, 2022). "Moreover, pDCs induce direct cytotoxicity of tumor cells through the expression of TNF-related apoptosis-inducing ligand (TRAIL) and Granzyme B. Furthermore, pDCs can produce CCR5 which mediates the recruitment of NK cells to the TME." (PMID 36011029, 2022). "Taken together, we could show that CIK cells in combination with crizotinib and nivolumab can enhance the anti-tumor immune response through FasL activation, leading to increased IFN-γ and granzyme B, but only in NCI-H2228 cells with EML4-ALK rearrangement." (PMID 35646685, 2022). "It was revealed that plasma cells, which are primarily found in the tumor and not blood, express the highest levels of GZMB, sharply contrasting peripheral blood naïve and IgM memory B cells that express low levels of the transcript." (PMID 35392082, 2022). "It was reported that GZMB from killer cells could cleave the GSDME directly and promote the occurrence of pyroptosis, which could further activate the anti-tumor immune response and inhibit tumor growth." (PMID 35957895, 2022). "Moreover, C2-ceramide exerts its anti-tumor activity by increasing the percentage of CD8+T cells and producing perforin and granzyme B." (PMID 36518255, 2022). "C5,6,7_CD8, which was predominantly composed of CD8+ T cells from tumor tissue and blood, exhibited high gene accessibility of cytotoxic molecules including GNLY, PRF1 and GZMB, with cells in C6_CD8 exhibiting the highest accessibility for these cytolytic molecules." (PMID 35668194, 2022). "The control of tumor growth by T cells is largely dependent on their effector function and the secretion of effector molecules, including the cytokine IFN-γ and the cytolytic protease granzyme B (GzmB)." (PMID 35103755, 2022). "The three-dimensional information provided by granzyme B based-PET (GZP-PET) imaging, a novel technology enabling a global view of effector cell activation, allows noninvasive visualization of the tumor microenvironment that can be used to assess immune response over time." (PMID 35214172, 2022). "Although transferred RepTILs were not proficient in the control of the growth of tumor implants, the expression of granzyme B (GrB) by a few CD103+CD8+ TRM cells demonstrates their tumor-killing potential." (PMID 35740548, 2022). "Tumor cells release EV PD-L1, which can interact with PD-1 on the surface of T cells, thereby inhibiting their effector function and reducing the release of the pro-inflammatory cytokines IFN-γ, IL-2, and granzyme-b." (PMID 35090497, 2022). "Furthermore, we observed that celastrol slightly reduced the infiltration of GzmB+ cells, while SHP099 treatment showed the opposite effect on both tumor and peritumoral areas, and the combination treatment produced a result in between singular treatments." (PMID 36120370, 2022).
tumor (continued). "Indeed, IL-33 expression correlated strongly with CD8A and granzyme B as well as genes like BATF3, IRF8, THBD, CLEC9, and XCR1 that are required for tumor antigen cross-presentation functionality of CD103+ dendritic cells (DCs)." (PMID 36256464, 2022). "Indeed, granzyme B and perforin were induced by the LY6G6D/CD3 TcE only when T cells were cocultured with LY6G6D-positive tumor cells." (PMID 36159851, 2022). "While cytotoxic lymphocytes are capable of tumor control in the absence of GzmB, the GzmB-exocytosis pathway is significant for cytotoxic function." (PMID 35460379, 2022). "On Day 4, for anti-PD-L1 both with and without anti-VEGF, higher percentages of CD8+ T cells and GzmB+CD8+ T cells were observed in tumor tissues in the HM-1 model." (PMID 34958105, 2022). "Meanwhile, a significant increase in Granzyme B+ CD8+ T cells was seen in the PLX-NP-P-aPD-1@Gel group compared with all other treatment groups, indicating an enhanced effector T cell population for stronger anti-tumor effects." (PMID 35387972, 2022). "Moreover, Ruxo increased TNF, IFN-γ, perforin, and IL-2 production by CD4+ TILs, essential effector molecules in anti-tumor immunity; similar increases of IFN-γ, perforin, and GzmB were also noticed in CD8+ TILs." (PMID 36008408, 2022). "We found SCT treatment markedly increased CD4+ T cell, B cell, and NKT cell fractions in spleens, NKT cells in lymph nodes, as well as increased Th1 and Th17, as well as granzyme B+, perforin+, and IFN‐γ+ CD8+ effector T cell populations in the tumor‐infiltrating T cells." (PMID 34747157, 2022). "The expressions of granzyme-B and perforin in CD8+ T cells were upregulated in 1 month and 3 months, which might be due to the increased tumor burden in patients as the median follow-up time after RFA was 3.4 months." (PMID 35203498, 2022). "Additionally, intracellular cytokine staining in YUMM3.3 tumor-infiltrating CTLs revealed a marked INHBA-induced decrease in IFNγ, TNFα, and GzmB protein levels." (PMID 35580932, 2022). "N1 neutrophils could directly play an anti-tumor role by modulating the expression levels of cytotoxic effectors, including tumor necrosis factor-α (TNF-α), granzyme B (GZMB), and elastase (ELANE)." (PMID 35784745, 2022). "Flow cytometry analysis of resected 4T1 tumors collected from a separate experiment showed that the combination treatment resulted in increased expression of IFNγ, TNFα, and granzyme B in intratumoral CD8+ T and NK cells, as well as an overall increase in tumor-infiltrating CD8+ T cells." (PMID 35840558, 2022). "Moreover, these mice showed significantly higher levels of IFN-γ and granzyme B, as well as a lower proportion of PD1+, LAG3+ and TIM3+ in CD8+ T cells in the tumor tissue, indicating a higher level of CD8+ T-cell activation." (PMID 36451817, 2022). "Directly, pDCs contact with tumor cells and induce cytolysis via TNF‐related apoptosis‐inducing ligand (TRAIL)‐dependent pathway and the secretion of cytotoxic cytokines such as TNF‐α, granzyme B (GZMB), and soluble TRAIL." (PMID 34964283, 2022). "Furthermore, our model also predicts that during anti-tumor inflammation (i.e. stimulation of IL-12 and IFN-γ), high levels of fat reduce the population of Granzyme B-producing Tc1 cells, as recently reported." (PMID 35983057, 2022). "Moreover, G9668 increased tumor invasion by cytotoxic CD8+ T cells and their expression of the activation markers IFN-γ and granzyme B." (PMID 35446348, 2022). "Moreover, the numbers of tumor-infiltrating cytotoxic CD8+ and granzyme B+ (GzmB+) immune cells were significantly increased in the MSC/RT group." (PMID 35835756, 2022). "Moreover, the tumor-bearing KO mice had decreased frequencies of tumor-infiltrating IFN-γ–producing, TNF-α–producing, and granzyme B–producing CD8+ T cells." (PMID 35143421, 2022).
tumor (continued). "Our research found that compared with high-dose anti-VEGFR2 combined with anti-PD-1, low-dose anti-VEGFR2 combined with anti-PD-1 down-regulated the expression of LAYN on tumor infiltrating exhausted CD8+T cells, increased the secretion of GZMB, and then enhanced the function of CD8+T cells." (PMID 36260222, 2022). "Blockade of B7-H5 could enhance the infiltration and Granzyme B production of CD8+ T cells and inhibit tumor growth in mouse tumor models." (PMID 35966819, 2022). "Effector genes such as GZMB, GZMH and KLRG1 were the marker genes in clonotypes shared by all tissues, while the clonotypes present only in tumor showed upregulated T-cell exhaustion genes (HAVCR2, LAG3, CTLA4, TIGIT, PDCD1, and ICOS) and activation genes (SELL and TNFRSF9)." (PMID 36185254, 2022). "Therefore, referring to macrophage categorization, mast cells are divided into anti-tumor MC1 and pro-tumor MC2 based on TNF, granzyme B (GZMB), IL9, VEGF-A, and C-X-C motif chemokine ligand 8 (CXCL8) expression." (PMID 36726981, 2022). "We also observed increases in the percentages of tumor-infiltrating lymphocytes (TIL) producing IFNγ and activation marker Granzyme B (GZMB), and a reduced fraction of FOXP3+ T regulatory cells, whereas the fraction of CD11b+ Ly6G+ neutrophils and F4/80+ CD11b+ macrophages remained constant." (PMID 35915084, 2022). "The anti-CD137 agonist urelumab can overcome transforming growth factor (TGF)-β-mediated inhibition of human NK-cell proliferation and anti-tumor function and preserve the expressions of NKG2D, granzyme B, and interferon-gamma (IFN-γ) in HER2-positive primary breast cancer." (PMID 36601109, 2022). "Since Granzyme B can be a component of eosinophil granules, these data suggest eosinophils co-cultured with EO771-GFP tumor cells may be degranulating." (PMID 35756626, 2022). "Control CD4+ T-cells cultured the same way, but without peptides, produced low amounts of IFN-γ, granulysin and granzyme B and displayed poor cytotoxic activity against MHC-II-positive Capan-1 cells, which shows that the peptide-specific T cells were recognizing the tumor cells in a specific manner." (PMID 35655709, 2022). "Moreover, the highest granzyme B (a cytotoxic protein produced by CD8+ T cells) signal was detected in the tumor tissues from HDDA-treated mice, further indicating the strong immunostimulation effect of the HDDA NBs." (PMID 36319625, 2022). "Furthermore, we provide evidence that this effect is associated with a reduction in regulatory T-cell recruitment and activity at oral tumor microenvironments and increased antitumoral cytotoxic CD8+ T-cell activity, characterized by Granzyme B production." (PMID 36016924, 2022). "Similarly, the percentage of activated CD44hi CD8+ T cells increased within both the spleen and tumor, while the percentage of IFN-ɣ+ and granzyme B+ CD8+ T cells increased within the spleen." (PMID 36059473, 2022). "Furthermore, adenosine signaling through A2BR favors tumor growth by supporting the recruitment of CD11b+Gr1+ MDSCs that impairs tumor infiltration by CD8+ T and NKT cells and their production of TNF-α, IFN-γ, and granzyme B." (PMID 36713558, 2022). "Combined with the observation that LINC01198’s activation in tumor cells increased IFN-γ, GzmB, and type I–related cytokine (i.e., CXCL10 and TNF-α) secretions, we hypothesized that LINC01198 regulated IFN signaling pathways in cancer cells." (PMID 36475797, 2022). "In this regard, TRM lymphocytes have been reported to express molecules involved in cytotoxic activities, such as granzyme B, perforin, IL-2 and IFN-γ, as well as exhaustion markers such as PD-1 and CTLA-4, likely representing tumor-specific effector cells induced by virus antigens." (PMID 36123711, 2022). "Besides, the functional CD8+ T cells, which produce various cytokines (TNFα, IFNγ, GZMB, and IL2), were increased in the tumor from VEGF-C mRNA group." (PMID 35301438, 2022).